MDM2 (MDM2 proto-oncogene)
Diseases named in the same sentence as MDM2 in open-access papers (continued):
Sharing a sentence is not in itself a finding about the gene and the disease.
aneurysm (1 paper, 2019). Bulging or ballooning in an area of an artery secondary to arterial wall weakening.
Anxiety (1 paper, 2018). Intense feelings of nervousness, tension, or panic often arise in response to interpersonal stresses. "Genetic reduction of MDM2 in adult new neurons did not affect overall locomotor activity or anxiety in either WT or Fmr1 KO mice but rescued behavioral deficits of Fmr1 KO mice." (PMID 29950602, 2018).
Arthritis (1 paper, 2025). Inflammation of a joint. "In models of arthritis induced by collagen, treatment with this MDM2 inhibitor elicited three major therapeutic effects: inhibition of pro-inflammatory cytokine networks, reduction of clinical arthritis scores, and inhibition of synovial inflammation." (PMID 40852730, 2025).
asthma (1 paper, 2024). "Furthermore, compared to the Asthma + oe-NC + IDF-11,774 group, the Asthma + oe-MDM2 + IDF-11,774 group demonstrated a significant increase in IL-4, IL-5, IL-13, and IgE levels." (PMID 39061007, 2024).
astroglioma (1 paper, 2017). "Another one of these genes is MDM2, which is described as an important regulator of tumorgenesis in astroglioma models." (PMID 28279172, 2017).
atopic dermatitis (1 paper, 2022). "A role in atopic dermatitis has been described for the MDM2-targeting Janus kinase and syk inhibitor Gusacitinib." (PMID 35681700, 2022).
autoimmune hepatitis (1 paper, 2021). Hepatitis caused by autoantibodies. "We ever tested that mdm4/mdm2 heterodimers were down-regulated in thymoma patients without autoimmune hepatitis/myocarditis." (PMID 35070964, 2021).
brain inflammation (1 paper, 2024).
bronchogenic carcinoma (1 paper, 1998). A lung carcinoma arising from the bronchial epithelium.
carcinoma in situ (1 paper, 2015). "MDM2 was highly expressed in so-called squamous dysplasia and carcinoma in situ." (PMID 25880782, 2015).
carcinosarcoma (1 paper, 2013). A malignant tumor composed of a mixture of carcinomatous and sarcomatous elements.
cartilaginous neoplasms (1 paper, 2024). "Several oncogenic signaling pathways have been implicated in the progression of cartilaginous tumors, such as those related to cell migration (IMP3) and cell cycle (CDK4, MDM2, and β-catenin), which should be better elucidated." (PMID 39368400, 2024).
Cerebellar hypoplasia (1 paper, 2011). Cerebellar hypoplasia is a descriptive term implying a cerebellum with a reduced volume, but a normal shape and is stable over time. "It will be of interest to determine whether Mdm2 gene expression levels are associated with cerebellar hypoplasia or behavioral defects in people." (PMID 21437245, 2011).
cervical squamous cell carcinoma (1 paper, 2019). A squamous cell carcinoma arising from the cervical epithelium. "Therefore, in this study, we investigated the frequency of PIK3CA and MDM2 mutations in Filipino patients with cervical squamous cell carcinoma." (PMID 31350972, 2019). "Twenty-eight formalin-fixed paraffin-embedded cervical squamous cell carcinoma and 16 non-malignant cervix tissue biopsies of Filipino patients were subjected to PIK3CA gene and MDM2 SNP309 (rs2279744) analysis." (PMID 31350972, 2019).
cervical tumours (1 paper, 2009). "The Mdm-2 positivity of the cervical tumour cells ranged from 0 to 100%, with no overall difference in frequency between specimens taken before (Mean±s.e.m.: 65.3±6.8%) and after RT (Mean±s.e.m.: 65.6±9.4%) (mean diff=0.32, s.d.=39.8, P=0.970)." (PMID 19672258, 2009).
chronic pancreatitis (1 paper, 2015). A chronic inflammatory process causing damage and fibrosis of the pancreatic parenchyma.
cleft lip (1 paper, 2020). Congenital defect in the upper lip where the maxillary prominence fails to merge with the merged medial nasal prominences.
Co-infection (1 paper, 2014).
colitis (1 paper, 2025). Inflammation of the colon.
degenerative intervertebral disc disease (1 paper, 2023). "The miR-140–3p affects bone marrow stromal cells (BMSCs) in degenerative intervertebral disc disease (IVD) by directly targeting KLF5 and interacting with the N–cadherin/MDM2/Slug axis, thereby regulating regenerative effects in degenerative IVD." (PMID 37325630, 2023).
dental fluorosis (1 paper, 2024). A condition that results from excessive fluoride ingestion during tooth development, resulting in tooth discoloration ranging from white streaks to brown stains and cracks or pits in the tooth enamel. "This suggests that HAT plays a crucial role in the transcriptional regulation of p21 and Mdm2, which is associated with H3K27 acetylation in dental fluorosis." (PMID 39273544, 2024).
diffuse astrocytoma (1 paper, 1997). A low-grade (WHO grade II) astrocytic neoplasm.
embryonal tumors of (1 paper, 2011).
endometrioid adenocarcinoma (1 paper, 2016). An adenocarcinoma characterized by the presence of malignant glandular epithelial cells resembling endometrial cells.
endometrioid tumor (1 paper, 2013). A benign, borderline, or malignant epithelial tumor of the female reproductive system characterized by the presence of glands and/or cysts lined by neoplastic cells that resemble endometrial cells.
endothelial dysfunction (1 paper, 2022). In vascular diseases, endothelial dysfunction is a systemic pathological state of the endothelium (the inner lining of blood vessels) and can be broadly defined as an imbalance between vasodilating and vasoconstricting substances produced by (or acting on) the endothelium.
epithelioid mesotheliomas (1 paper, 2015). "Sarcomatoid/biphasic and epithelioid mesotheliomas showed different MDM2 and HIF1alpha expression levels and were characterized by different levels of necrosis, proliferation and inflammation." (PMID 26544728, 2015).
epithelioid sarcoma (1 paper, 2022). An aggressive malignant neoplasm of uncertain differentiation, characterized by the presence of epithelioid cells forming nodular patterns.
esophageal liposarcoma (1 paper, 2023). "She underwent endoscopic resection of the mass and was diagnosed with a five-centimeter long, well-differentiated esophageal liposarcoma, confirmed with fluorescence in situ hybridization for MDM2 gene locus amplification." (PMID 38024013, 2023).
fibroids (1 paper, 2012). "Interestingly, we were able to show that antagonizing MDM2 induces the activity of genes associated with senescence (p21) as well as those with apoptosis (BAX) in leiomyoma cells in vitro." (PMID 22233735, 2012). "Herein, we have used tissue explants taken from leiomyomas and matching myometrium to analyze the effects of an MDM2 antagonist and possible different sensitivities of the fibroids and their matching tissue of origin." (PMID 22233735, 2012). "Nevertheless, the higher sensitivity of the leiomyoma tissue against the inhibition of MDM2 compared to surrounding myometrium corresponds to a higher in vivo expression of p14Arf and thus likely exists in vivo as well." (PMID 22233735, 2012). "Accordingly, a combination e.g. of a GnRH antagonist and a MDM2 antagonist may be a favourable approach for the treatment of fibroids." (PMID 22233735, 2012). "Accordingly, it can be speculated that leiomyomas may be more sensitive against MDM2 inhibition than matching myometrium." (PMID 22233735, 2012). "This makes antagonizing MDM2 an interesting approach towards the growth control of fibroids." (PMID 22233735, 2012).
follicular dendritic cell sarcoma (1 paper, 2024). A neoplasm composed of spindle to ovoid cells which have morphologic and immunophenotypic characteristics of follicular dendritic cells. "In summary, we presented a rare case of follicular dendritic cell sarcoma arising from the renal parenchyma, with detailed morphological features and confirmed MDM2 amplification by FISH." (PMID 38297323, 2024).
follicular thyroid carcinomas (1 paper, 2024).
Fulminant hepatitis (1 paper, 2024). Acute hepatitis complicated by acute liver failure with hepatic encephalopathy occurring less than 8 weeks after the onset of jaundice. "Previous studies have reported implications of MDM2 and COP1 that targeted STAT3 for degradation in tumorigenesis, and involvement of MDM2 in RACK1-abrogated HDAC1 degradation during the pathogenesis of fulminant hepatitis." (PMID 39024388, 2024).
gallstones (1 paper, 2021). Solid crystalline precipitates in the biliary tract, usually formed in the gallbladder, resulting in the condition of cholelithiasis.
gastritis (1 paper, 2016). Inflammation of the stomach. "This study aimed to investigate the characteristics of H. pylori associated gastritis, clarithromycin resistance, Mdm2 polymorphisms, and significant risk factors of H. pylori associated gastritis among the Thai population." (PMID 27042174, 2016).
gastroesophageal junction adenocarcinoma (1 paper, 2021). A carcinoma that arises from glandular epithelial cells of the esophagogastric junction. "The same authors also published a separate report indicated that in a patient with gastroesophageal junction adenocarcinoma MDM2 and EGFR amplifications was found, 3.5% out of 100,000 samples had MDM2 amplification." (PMID 34367148, 2021).
giant cell tumor (1 paper, 2018). A benign, intermediate, or malignant tumor that arises from the bone or soft tissue. "In this study, the aim is to verify, by immunohistochemistry, the expression of IGF1, MDM2, STAT1, and RAC1 and investigate their potential relationship with GCT recurrence, in a large cohort of patients with a giant cell tumor of the bone." (PMID 29651441, 2018).
gliosarcoma (1 paper, 2021). A rare histological variant of glioblastoma (WHO grade IV) characterized by a biphasic tissue pattern with alternating areas displaying glial and mesenchymal differentiation (WHO).
glomerular disorder (1 paper, 2024). A disease involving the renal glomerulus. "The accumulation of P62 increases MDM2-Notch1 activities, leading to glomerular disorders in DN." (PMID 38993555, 2024).
Helicobacter pylori (1 paper, 2023).
hemophilia (1 paper, 2025). Hemophilia is a genetic disorder characterized by spontaneous hemorrhage or prolonged bleeding due to factor VIII or IX deficiency.
Hydrocephalus (1 paper, 2020). Hydrocephalus is an active distension of the ventricular system of the brain resulting from inadequate passage of CSF from its point of production within the cerebral ventricles to its point of absorption into the systemic circulation.
Hyperkeratosis (1 paper, 2021). Hyperkeratosis is a histopathological term defining a thickened stratum corneum and may be present in many different skin conditions, with many possible overlaps. "Mdm2, which had previously been shown to cause hyperkeratosis in MdM2-overexpressing mice, was amongst these genes and inhibition of Mdm2 by nutlin-3 prevented hyperkeratosis in these rat ARCI models." (PMID 33652877, 2021).
hypogonadism (1 paper, 2025). A disorder characterized by decreased function of the gonads. "Variants in MDM2 (OMIM:618681) have been associated with Lessel–Kubisch syndrome, a recessive condition with phenotypic overlap with Werner syndrome, including short stature, craniofacial dysmorphism, hypogonadism, and premature greying." (PMID 40913728, 2025).